EZH2 (enhancer of zeste 2 polycomb repressive complex 2 subunit)
Diseases named in the same sentence as EZH2 in open-access papers (continued):
Sharing a sentence is not in itself a finding about the gene and the disease.
multiple myeloma (continued). "The overexpression of NSD2 in multiple myeloma is a consequence of its regulation by a strong IgH enhancer in the NSD2 gene, and this NSD2 overexpression impairs the binding of EZH2 and the reprogramming of the myeloma epigenome because of locally altering the H3K36 and H3K27 methylation patterns." (PMID 36011043, 2022). "In addition, dual inhibition of H3K9me2 and H3K27me3 with the G9a inhibitor, UNC0638 (1 μM), and the EZH2 inhibitor, GSK126 (1 μM), suppresses multiple myeloma cell proliferation by inducing cell cycle arrest and apoptosis." (PMID 35409271, 2022). "Investigating the survival prognosis in multiple myeloma (MM) patients, we have shown that PRC2 core genes, EZH2, SUZ12 and EED, were significantly overexpressed in MM cells compared to normal plasma cells, making these cells sensitive to EPZ-6438, an inhibitor of EZH2." (PMID 34202528, 2021). "Interestingly, this PHF19 high myeloma cell subtype also exhibited high expression of genes involved in cell cycle including HELLS, EZH2, TYMS, ZWINT, and MKI67." (PMID 34857028, 2021). "Interestingly, this PHF19high myeloma cell subpopulation seems to be the cell cycling fraction as they also exhibited high expression of genes involved in cell cycling including HELLS, EZH2, TYMS, ZWINT, and MKI67." (PMID 34857028, 2021). "EZH2-overexpression has been recently described within the context of MM, demonstrating its negative prognostic value: specifically, authors have reported on increased EZH2 during disease progression, going from MGUS, to smoldering myeloma, to MM." (PMID 33076518, 2020). "EZH2 targeting significantly reduced the median number of viable myeloma cells by 35% (P = 0.004) in 9/17 patients whereas MM cells of 8 patients were not significantly affected by the EZH2 inhibitor." (PMID 30285865, 2018). "Finally, in multiple myeloma, PTC-209 showed a synergistic activity when combined with other epigenetic inhibitors (such as those targeting EZH2 and BET)." (PMID 30574454, 2018). "This suggests that a therapeutic index exists for the response to EZH2 inhibition between myeloma and non-malignant cells." (PMID 28362441, 2017). "In contrast, previous studies in myeloma, identifying other genes thought to be regulated by EZH2, did not identify a unifying transcriptional pattern in responding vs non-responding cell lines." (PMID 28362441, 2017). "In order to gain insights into the biology of EZH2 without disruption of the PRC2 complex in myeloma, we took advantage of the recent discovery of potent and selective EZH2 inhibitors." (PMID 28362441, 2017). "In the current study, we explored whether EZH2 inhibition using the selective inhibitors UNC1999 and GSK343 had anti-myeloma effects." (PMID 26755663, 2016). "To determine whether the enhanced binding of EZH2 may play a functional role in myeloma cell survival, we treated MMSET-high and MMSET-low cells with recently described small molecule inhibitor of EZH2." (PMID 25188243, 2014). "EZH2 and EPC1 are two polycomb-related genes upregulated in the myeloma SP." (PMID 23469177, 2013). "Moreover, CCNB1, AURKB, EZH2 and PSMA5 were also upregulated in the SPs from eight primary myeloma samples." (PMID 23469177, 2013). "H3K27Me3 levels were also decreased in KMS18 and OPM-2 but not in the two sensitive cell lines, suggesting that the induction of cell death by DZNep in myeloma cells is not mediated through its effect on EZH2 or H3K27Me3." (PMID 21720561, 2011). "The key issue we also need to consider is that TIGIT binds to CD112 and CD113 ligands, in addition to CD155 ligands, on the surface of myeloma cells, but our experiments did not observe significant changes in the expression of the remaining ligands after EZH2 inhibitor treatment." (PMID 37239949, 2023). "Further, it is not clear that EZH2 inhibition is an effective treatment strategy in all myelomas." (PMID 29774113, 2018).
multiple myeloma (continued). "STAT3 protein binding at the EZH2 promoter was significantly increased in SGC7901 cells, and was increased 6.18-fold with IL-6 stimulation, which is consistent with the results of studies showing that EZH2 protein expression is induced by IL-6 in multiple myeloma cell lines." (PMID 27938379, 2016). "In addition, the sensitivity of myeloma cells to DZNep is not directly related to inhibition of EZH2 or H3K27 trimethylation, suggesting the DZNep may also act through non-epigenetic mechanisms." (PMID 21720561, 2011).
acute myeloid leukemia (82 papers, 2011 to 2026). Acute myeloid leukemia (AML) is a group of neoplasms arising from precursor cells committed to the myeloid cell-line differentiation. "In acute myeloid leukemia patients, EZH2 mutations frequently co-occurred with CEBPA (67%), ASXL1 (50%), TET2 and RAD21 mutations (33% each)." (PMID 33845873, 2021). "EZH2 was mutated in 6/51 acute myeloid leukemia patients (12%) and 7/7 patients with other myeloid neoplasms." (PMID 33845873, 2021). "We have examined the importance of cellular context for Ezh2 loss during the evolution of acute myeloid leukemia (AML), where we observed stage-specific and diametrically opposite functions for Ezh2 at the early and late stages of disease." (PMID 30890554, 2019). "The purpose of the present work was to determine the incidence and clinical implications of somatic EZH2 mutations in 714 patients with de novo acute myelogenous leukemia by sequencing the entire coding region." (PMID 23613835, 2013). "Overall, these results showed EZH2 mutation in de novo acute myeloid leukemia as a recurrent genetic abnormality to be associated with lower blast percentage in BM and -7/del(7q)." (PMID 23613835, 2013). "In the last 3 years, alone mutations in the genes TET2, IDH1, IDH2, DNMT3a, and EZH2 have all been found in patients with myeloproliferative neoplasms (MPNs), myelodysplastic syndromes (MDSs), and/or acute myeloid leukemia (AML)." (PMID 21811504, 2012). "Interference of EZH2 function by the small-molecule histone methyltransferases inhibitor, DZNep, is reported to increase ROS levels in acute myeloid leukemia cells like in Bmi1-deficient mice." (PMID 22606246, 2012). "For example, one shared downstream target of PFAs and DMGs with PRC2-impaired tumors is the zinc-finger transcription factor pleomorphic adenoma gene 1 (PLAG1), which is de-repressed in EZH2-mutated acute myeloid leukemia (AML)." (PMID 34762160, 2022). "A 65-year-old woman was diagnosed with acute myeloid leukemia (AML-M2a subtype) on July 18, 2023,accompanied by mutations in FMS‐like tyrosine kinase 3 (FLT3)-ITD, NPM1, TET2, EZH2, and other genes." (PMID 39544304, 2024). "E2F4 represses the MAPK signaling pathway by binding with EZH2, thereby inhibiting the progression of acute myeloid leukemia." (PMID 37349788, 2023). "A recent study also identified the context-specific roles of EZH2 in Acute Myeloid Leukemia (AML) 11, 12, which is a rapidly progressive and poor-prognosis malignancy arising from hematopoietic stem cells." (PMID 34093860, 2021). "Epigenetic gene silencing by DNA methylation and histone methylation by EZH2 play an important role in the development of acute myeloid leukemia (AML)." (PMID 34968294, 2021). "The aim of this study was to analyze the EZH2 expression in pediatric patients with MDS and its association with karyotypes and evolution to acute myeloid leukemia (AML)." (PMID 31886200, 2019). "Genes associated with the pathogenesis of acute myeloid leukemia, such as DNMT3A, NRAS, RUNX1, EZH2, and KRAS, were more commonly mutated in the hypermethylation group." (PMID 30635552, 2019). "This is exemplified by the observation that whereas mutational loss of EZH2 promotes the development of myelodysplastic syndrome (MDS), it attenuates MDS progression to acute myeloid leukemia by suppressing expression of the leukemic oncogene Hoxa9." (PMID 28758948, 2017). "Both overexpression and loss-of-function mutations have been detected in myelodysplastic syndrome (MDS) and acute myeloid leukemia (AML) suggesting that EZH2 can function as tumor suppression and as an oncogene in myeloid malignancies." (PMID 27793053, 2016). "DZNep treatment has been demonstrated to decrease levels of EZH2 in solid tumors and acute myeloid leukemia." (PMID 21720561, 2011). "Notably, increased glutamate levels in EZH2-mutant acute myelogenous leukemia drive BCAA production by BCAT1 to support mTORC1 and to restrict αKG levels." (PMID 40924473, 2025).
acute myeloid leukemia (continued). "Case presentation: In this study we described a patient who underwent hematopoietic stem cell transplantation due to acute myeloid leukemia and subsequently developed triple-negative myeloproliferative neoplasms with mutations in the ASXL1, SETBP1 and EZH2 genes 9 years later." (PMID 39907609, 2025). "Notably, increased glutamate levels in EZH2-mutant acute myelogenous leukemia drive BCAA production by BCAT1 to support mTORC1 and also to restrict aKG levels." (PMID 38854072, 2024). "In addition to its established role in myeloid malignancies, EZH2 has been implicated in the development of T-cell acute lymphoblastic leukemia (T-ALL) and acute myeloid leukemia (AML)." (PMID 38036730, 2023). "In support of this notion, EZH2 aberrations in acute myeloid leukemia (AML) may be in fact three times more frequent if we consider inactivation due to AS." (PMID 34356101, 2021). "Furthermore, loss-of-function mutations and deletions of EZH2 are also detectable in other cancers including T-lineage acute lymphoblastic leukemia (T-ALL) and core binding factor acute myeloid leukemia." (PMID 33003334, 2020). "The association between HOXA-AS2 and EZH2 has also been confirmed in PC, OSCC, acute myeloid leukemia (AML), and glioma." (PMID 38311789, 2024). "Loss-of-function (LOF) mutations of EZH2 occur in several cancers including T-cell Acute Lymphoblastic Leukemia (T-ALL) and Acute Myeloid Leukemia (AML)." (PMID 36105358, 2022). "The EZH2 gene is located on chromosome 7q36.1, a region frequently deleted in acute myeloid leukemia (AML), myelodysplastic syndromes (MDS), and myeloproliferative neoplasms (MPN)." (PMID 33845873, 2021). "Interestingly, the R502 of EZH2, a residue in the YPB domain, was also mutated in several cases of acute myeloid leukemia to generate an R502Q mutant; however, whether this mutation alters the YY1-EZH2 interaction needs to be elucidated in future studies." (PMID 34065631, 2021). "In MDS and MDS-derived acute myeloid leukemia (AML), EZH2 over-expression is correlated with poor prognosis." (PMID 33003334, 2020). "However, in acute myeloid leukemia (AML), loss of the histone methyltransferase EZH2 and subsequent reduction of histone H3K27 trimethylation is identified as a novel pathway of acquired resistance to tyrosine kinase inhibitors (TKIs) and cytotoxic drugs in AML." (PMID 29556394, 2018). "Regarding the MPN/AML transformation, mutations in genes encoding epigenetics modifiers such as ASXL1, IDH1, IDH2, EZH2, and TET2 are associated with nearly 30% of secondary leukemia transformations and de novo acute myeloid leukemia." (PMID 29515972, 2018). "EZH2 is highly expressed in high-risk myelodysplastic syndrome (MDS) and in acute myeloid leukemia (AML) arising from a pre-existing MDS." (PMID 26497210, 2016). "Low EZH2 expression was associated with high percentages of blasts, shorter survival, and increased transformation of MDS into acute myeloid leukemia (AML)." (PMID 26812882, 2016). "Here, we present a case of a patient who underwent hematopoietic stem cell transplantation (HSCT) due to acute myeloid leukemia (AML) and developed from donor cells triple-negative (TN) myeloproliferative neoplasms with mutations in the ASXL1, SETBP1 and EZH2 genes." (PMID 39907609, 2025). "DZNep was extensively studied because of its suppressive roles on EZH2 in tumors, such as malignant peripheral nerve sheath tumor, prostate cancer, head and neck squamous cell carcinoma, gastric cancer, and acute myeloid leukemia (AML)." (PMID 34930462, 2021). "EZH2 inhibitors, EPZ-6438 and GSK2816126, for instance, showed anti-neoplastic activity in acute myeloid leukemia (AML) and are currently in clinical trials of lymphoma treatment." (PMID 30634442, 2019).
acute myeloid leukemia (continued). "However, both overexpression and loss-of-function mutations of EZH2 gene being detected in myelodysplastic syndrome (MDS) and acute myeloid leukemia (AML) suggests that EZH2 can function as tumor suppressor gene or as an oncogene in myeloid malignancies." (PMID 29556394, 2018). "To investigate the influence of EZH2 expression on overall survival and transformation into acute myeloid leukemia (AML), we divided patients into two EZH2 expression groups: low EZH2 expression (RMFI value ≤ median value) and high EZH2 expression (RMFI value > median value)." (PMID 26812882, 2016). "Recently, a combined epigenetic therapy, involving the histone methyltransferase EZH2 inhibitor and a HDAC inhibitor, was shown to be effective in acute myeloid leukemia (AML) cells." (PMID 21541038, 2011). "Non-driver mutations, such as those in ASXL1, EZH2, TET2, SRSF2, and IDH1/IDH2, have been found to exacerbate disease severity, accelerate progression, and increase the risk of transformation to acute myeloid leukemia (AML)." (PMID 39434124, 2024). "It inhibits ferroptosis in TSCC cells by inhibiting miR-125b-5p and enhancing SLC7A11, while in acute myeloid leukemia (AML), muscle ARNT-Like protein-1 (Bmal1) prevented RSL3-induced ferroptosis through EZH2-mediated EBF3 methylation to inhibit the expression of EBF3 and ALOX15." (PMID 39518098, 2024). "The EZH2 mediated H3K27me3 could activate the cGAS-STING pathway, leading to secretion of cytokines and chemokines and activation of macrophages upon coculture with acute myeloid leukemia cells." (PMID 40375990, 2025). "Inhibitors targeting EZH2 such as 3-Deazaneplanocin A (DZNep), GSK126, EI1, and UNC1999 exhibit a proliferation suppression effect on various tumor cells or cancer models, including Acute Myeloblastic Leukemia (AML), lymphoma, gastric cancer, breast cancer, and MLL-rearranged leukemia 140-145." (PMID 34671219, 2021). "Moreover, in AML (adult acute myeloid leukemia) cells, 50% of the genes downregulated by PRMT5 inhibition were partially rescued in expression upon inhibition of EZH2 activity, providing evidence of the critical role for PRC2-EZH2 in methylation and subsequent repression of these target genes." (PMID 33804165, 2021).
lung adenocarcinoma (79 papers, 2012 to 2025). A carcinoma that arises from the lung and is characterized by the presence of malignant glandular epithelial cells. "In lung adenocarcinoma, loss of function of EZH2 was observed to increase the number of tumor lesions, which was attributed to activation of AKT and ERK through insulin-like growth factor 1 (IGF1) signaling." (PMID 38036730, 2023). "We also found that high EZH2 level are associated with an impaired prognosis of patients with lung adenocarcinomas." (PMID 33256112, 2020). "Although squamous cell lung carcinomas had increased EZH2 expression levels compared to lung adenocarcinomas, the only significant association observed with increased EZH2 expression was lymph node metastasis." (PMID 33050946, 2020). "Our previous report demonstrated that EZH2 positivity in lung adenocarcinoma was associated with higher metabolic activity in 18F-fluorodeoxyglucose positron-emission tomography/computed tomography (18F-FDG PET/CT)." (PMID 31042721, 2019). "Conditional EZH2 knock-out (KO) mice were also used to demonstrate that EZH2 inactivation increased lung adenocarcinoma aggressiveness in mice carrying the KRAS mutation." (PMID 34991274, 2018). "It has been determined that different amino acid substitutions in oncogenic KRAS differently modulate EZH2 expression in lung adenocarcinoma showing that KRASG12C is associated with higher EZH2 expression." (PMID 27793053, 2016). "Higher inflammatory markers are associated with unsatisfactory prognoses in NSCLC patients, according to a paper we just published; these results imply that the effects of EZH2 on lung adenocarcinoma may be tightly linked to inflammatory factors." (PMID 37069494, 2023). "Moreover, a higher level of EZH2 expression is associated with an inferior prognosis for lung adenocarcinoma patients." (PMID 37069494, 2023). "In Kras-driven lung adenocarcinoma, deletion and mutations of EZH2 are frequently present, and loss-of-function alterations are observed, which demonstrated that EZH2 might act as a tumor suppressor." (PMID 32723346, 2020). "Expression of E2F1’s well-known downstream target genes was significantly upregulated in subgroup F, indicating that E2F1 was highly activated in subgroup F and that E2F1-mediated regulation of EZH2 may be a key genetic event associated with poor prognosis in lung adenocarcinoma." (PMID 22970185, 2012). "In lung adenocarcinoma, the inhibition of EZH2 reduced the malignant potential of lung adenocarcinoma and increased the sensitivity of cells to platinum and vascular endothelial growth factor receptor 2 targeted therapy." (PMID 40028035, 2025). "Evidence indicates that CAMK2A promotes tumor-initiating capacity in lung adenocarcinoma by enhancing SOX2 expression through EZH2 phosphorylation, highlighting its complex involvement in tumor biology." (PMID 41180485, 2025). "For example, targeting the menin-PRC2 complex (which includes EZH2) suppresses lung adenocarcinoma growth by mediating H3K27me3-dependent silencing of the oncogenic growth factor pleiotrophin (PTN)." (PMID 40599544, 2025). "The miR-126/EZH2 axis has been described in lung adenocarcinoma, where restoring miR-126 levels inhibits EZH2, enhancing radiosensitivity, inhibiting cell migration, and promoting apoptosis." (PMID 39796183, 2025). "For instance, KDR inhibitors have been shown to decrease the malignant potential of lung adenocarcinoma cells by downregulating EZH2 expression and increasing sensitivity to chemotherapy." (PMID 38260532, 2025). "In preclinical research, JQEZ5, a EZH2 inhibitor, has shown anti-tumor activity in mice and human lung adenocarcinoma model of high EZH2 expression." (PMID 38347129, 2024). "We first evaluated the effect of EZH2 KD on human lung adenocarcinoma A549 cell growth, as 2D and 3D spheroid cultures in a 384-well plate." (PMID 37992808, 2024).